LYVE1 (lymphatic vessel endothelial hyaluronan receptor 1)
Diseases named in the same sentence as LYVE1 in open-access papers (continued):
Sharing a sentence is not in itself a finding about the gene and the disease.
atherosclerosis (8 papers, 2016 to 2025). A disease characterized by the build-up of fatty material and calcium deposition in the arterial wall resulting in partial or complete occlusion of the arterial lumen. "We identified an atherosclerosis-associated LYVE-1+ res-like macrophage population via RNAseq analysis, which was found to trigger VSMC transdifferentiation to osteoblast/chondrocyte-like cells, in a CCL24-dependent manner." (PMID 35159221, 2022). "We show that LYVE1+ resident macrophages are atheroprotective, and identify biological pathways related to actin filament organization, of which alteration accelerates atherosclerosis." (PMID 39231480, 2024). "We therefore assessed the accumulation of LYVE1+ macrophages at various stages of atherosclerosis in mice." (PMID 39231480, 2024). "We also identified a separate population of LYVE1+ macrophages (My.6) also expressing high levels of TREM2, a gene previously implicated in antiinflammatory macrophages in murine atherosclerosis." (PMID 37471165, 2023). "Considering that one of the identified populations of macrophages was specifically derived from cells of the atherosclerosis-prone AA&R, we gained further insight into the role of LYVE-1 res-like macrophages in the pathogenesis of atherosclerosis." (PMID 35159221, 2022). "Moreover, the shift in the balance between M1-like VEGFA+ and M2-like Lyve1+ macrophages may play a critical role in the progression of atherosclerosis." (PMID 40594772, 2025).
colorectal cancer (8 papers, 2015 to 2024). A primary or metastatic malignant neoplasm that affects the colon or rectum. "Furthermore, the LYVE-1+ macrophage cluster is heavily enriched for C1q genes, which are associated with an immunosuppressed tumor microenvironment in human patients with colorectal cancer." (PMID 38717149, 2024). "By integrating scRNA-seq data, immunofluorescent staining, and TCGA datasets, we identified that FOLR2+LYVE1+ macrophages in colorectal cancers, and exhibited steady-state macrophage transcriptional profile and moderate-to-low energy metabolic features." (PMID 36172359, 2022). "Despite the existence of multiple well-characterized colorectal-cancer-associated macrophage subgroups, including C1QC+ TAMs, SPP1+ TAMs, and FCN1+ TAMs, we identified a kind of tumor-resident FOLR2+ LYVE1+ macrophage subgroup in colorectal cancer." (PMID 36172359, 2022). "ANRIL expression was correlated with the increased expressions of VEGF-C, VEGFR3, LYVE-1, and tube formation in both colorectal cancer cell lines and surgical specimens." (PMID 31616631, 2019). "The existence and function of two states of exhausted CD8+ T (Tex) subtypes in colorectal cancer, and FOLR2+ LYVE1+ macrophages indicating unfavorable prognosis in colorectal cancer were identified and validated." (PMID 36172359, 2022). "ANRIL downregulation reduced lymphatic metastasis rate, lymphatic microvessel density (LMVD), and the expressions of VEGF-C, VEGFR3, LYVE-1, representing the potential role of ANRIL as a therapeutic target in colorectal cancer." (PMID 31616631, 2019). "We previously detected LYVE-1 expression, lymphatic microvessel and LMVD in human colorectal cancers, and evaluated their correlation with lymphangiogennesis, lymphatic metastasis, VEGF-C, −D and VEGFR-3, and prognosis in patients with colorectal cancer." (PMID 26187792, 2015). "Since PZH inhibits tumor metastasis, we examined the expression of VEGF-C, VEGFR-3, and LYVE-1, and found that PZH downregulated these genes expression, indicating that PZH could inhibit tumor lymphangiogenesis in colorectal cancer." (PMID 37286729, 2023).
diabetes (8 papers, 2008 to 2021). "In diabetes, wound healing is impaired, due to decreased numbers of macrophages (F4/80+, Lyve-1+, podoplanin+) and lymph vessels." (PMID 18430230, 2008).
gastric cancer (8 papers, 2013 to 2024). A primary or metastatic malignant neoplasm involving the stomach. "A notable case is the gene LYVE1, which emerges as the most influential gene in classifying renal carcinoma but ranks as the least significant in gastric carcinoma classification." (PMID 39596491, 2024). "One study has demonstrated that LYVE1 was upregulated in gastric cancer, and overexpression of LYVE1 positively correlated with perineural invasion and lymph node in gastric cancers." (PMID 33717664, 2021). "LYVE-1 also plays a positive role in the lymph node metastasis of gastric cancer." (PMID 38791985, 2024). "Similarly, Da and colleagues showed that curcumin treatment reduces the density of intratumoral LYVE1-positive vessels in mice xenotransplanted with gastric cancer cells." (PMID 34206901, 2021). "And the expression of LYVE1 might be a biomarker to predict the existence of regional lymph node metastasis in early gastric cancer." (PMID 33717664, 2021). "In this study, the density of lymphatic vessels measured by the expression of D2-40 and LYVE-1 and VEGF-C/D immunoreactivity in gastric cancer specimens was investigated by immunohistochemistry." (PMID 23238856, 2013).
Obesity (8 papers, 2016 to 2024). Accumulation of substantial excess body fat. "Consistent with previous reports, obesity enhanced the proportion of Itgax+ (encoding CD11c) and Cd9+ ATMs (cluster 0) and Plac8+ monocytes (cluster 4) and reduced the proportion of Lyve1+ and Cd163+ ATMs (cluster 1) and Lyz1+ monocytes." (PMID 34676827, 2021). "Increased expression of the Lyve1 gene associated with GALP administration may indicate restoration of lymphatic function that has been impaired by obesity." (PMID 37958806, 2023). "Since obesity is characterized by recruitment of ATMs, and a comparative loss of resident ATMs22, we tested whether obesity led to a change in turnover of Lyve1+Tim4+ resident ATMs." (PMID 34290249, 2021). "Moreover, obesity increased Ant2 expression in Itgax–, Lyve1+, and Cd163+ ATMs, although Ant2 expression was unchanged by LPS treatment in BMDMs." (PMID 34676827, 2021). "Our lab is currently seeking answers to these important questions, in the context of obesity and metabolic syndrome, in PAI-1fx/fx mice crossed to Lyve1, Prox1, or Myh11 Cre-lines." (PMID 35308249, 2022).
ovarian carcinoma (8 papers, 2006 to 2025). A malignant neoplasm originating from the surface ovarian epithelium. "While LYVE1 + macrophages are important for the maintenance of lymphatic vessels under normal conditions, they have recently been linked to ovarian cancer metastasis." (PMID 36723776, 2023). "By contrast, Lyve-1 expression is also associated with a specific macrophage subpopulation that was found to promote ovarian cancer progression and metastasis." (PMID 32479261, 2020). "This is the first report of LVD in ovarian cancer as measured by LYVE-1, one of the best-characterised markers for lymph vessels." (PMID 16685274, 2006). "Further analysis showed that ovarian cancer patients with high level of CITED2, LYVE1, OGN, RAP1A, and TBC1D22A had a poor prognosis that that with level of CITED2, LYVE1, OGN, RAP1A, and TBC1D22A (all p < 0.05)." (PMID 37784081, 2023). "The protein level of CITED2, LYVE1, OGN, RAP1A, and TBC1D22A were higher in ovarian cancer tissues than that in normal tissues." (PMID 37784081, 2023).
glioma (7 papers, 2018 to 2025). A benign or malignant brain and spinal cord tumor that arises from glial cells (astrocytes, oligodendrocytes, ependymal cells). "Prox1+/LYVE‐1+ cells were distributed in some lymphatic vessels as well as among vascular endothelial cells and glioma cells." (PMID 31960509, 2020). "Staining for Prox1 revealed abundant LYVE1+/Prox1+ tumor cells and lymphatic endothelial cells in gliomas." (PMID 31960509, 2020). "The average optical density value for LYVE‐1+ staining was significantly greater in glioma tissue than in normal tissue." (PMID 31960509, 2020). "No LYVE‐1 staining was observed in normal brain tissue, but LYVE‐1+ cells were found in glioma samples where they were mainly distributed among small blood vessels and capillary endothelial cells." (PMID 31960509, 2020). "The present immunohistochemical analysis revealed upregulation of Prox1 and HIF‐1α in some glioma tissues as well as the differentiation of nestin+ tumor stem cells into LYVE‐1+ lymphatic vessels." (PMID 31960509, 2020). "In summary, we observed up‐regulated co‐expression of Prox1 and HIF‐1α in gliomas as well as the differentiation of nestin+ tumor stem cells into LYVE‐1+ lymphatic endothelial cells that formed lymphatic vessels." (PMID 31960509, 2020). "Additionally, many vessels formed by LYVE‐1+/CD34+ cells were seen in the gliomas, along with many red blood cells." (PMID 31960509, 2020). "Specimens from seven glioma cases were analyzed by immunohistochemical staining for CD34, lymphatic endothelial hyaluronic acid receptor 1 (LYVE‐1), prospero‐related homeobox 1 (Prox1), nestin, and hypoxia‐inducible factor 1α (HIF‐1α)." (PMID 31960509, 2020). "Three types of vessels were observed in glioma specimens: LYVE‐1+ lymphatic vessels, CD34+ blood vessels, and LYVE‐1+/CD34+ blood vessels." (PMID 31960509, 2020). "As for both LYVE1 and OTP, to our knowledge this study presents the first evidence of hypoxia-related regulation and clinical correlation in IDH1mut glioma patients." (PMID 30257451, 2018). "Therefore, it can be concluded that rapid proliferation of glioma cells triggers hypoxia within the tumor cells, activating downstream genes including HIF‐1α and Prox1 and leading to tumor cell differentiation and expression of LYVE‐1." (PMID 31960509, 2020).
pancreatic cancer (7 papers, 2014 to 2025). "Our study found that the expression level of LYVE-1 increased in pancreatic cancer stem cells after treatment with CCL21, which supply the direct molecular mechanism that CCL21 was responsible for mediating lymph node metastasis." (PMID 27505247, 2016). "In their study, Patel & Mukherjee66 developed a neural network model using four urine biomarkers (REG1A, REG1B, LYVE1, and TFF1) to predict locally progressed pancreatic cancer." (PMID 40269234, 2025). "In another study, a neural network algorithm was employed to screen 140 datasets of individuals diagnosed with pancreatic cancer, for gene biomarkers in urine samples, namely REG1A/1B, LYVE1, TFF1, and CA19-9." (PMID 36358800, 2022). "The illustration also indicates that age, sex, plasma CA19-9, creatinine, LYVE1, REG1B, TFF1, and REG1A have a positive correlation in the diagnosis of pancreatic cancer meaning that they are statistically significant predictors of pancreatic cancer diagnosis." (PMID 40269234, 2025). "For example, bone marrow-derived macrophages (BMDMs) can express LYVE1, PROX1, and PDPN, and form lymphatic-like structures in vitro and LYVE1 + PROX1 + PDPN + bone marrow derived cells undergo lymphatic vascular mimicry during neo-lymphangiogenesis in VEGFC-expressing pancreatic tumors in mice." (PMID 38218743, 2024).
breast tumor (6 papers, 2006 to 2019). "It is very well known that COX-2 induces angiogenesis and lymphangiogenesis through production of VEGFC and VEGFD, and upregulation of PI3K/Akt signalling and COX-2 overexpression can also induce LYVE-1 over expression in mouse breast tumours." (PMID 31277414, 2019). "Immunochemical detection of LYVE-1 showed that lymph vessels had a predominant peritumoral localization in the breast tumors formed by MDA cells and that they were very scarce in the tumors formed by the MDA-TRβ cells." (PMID 27806339, 2016). "The clinical significance of these results is stressed by the finding that NCoR and TRβ transcripts correlate negatively with those of the lymphangiogenic genes and the lymphatic vessel marker LYVE-1 in human breast tumors." (PMID 27806339, 2016). "In our study, LYVE1 immunostaining revealed that lymph vessels were mainly present in the peritumoral lesions of breast tumors and were rarely observed inside the tumor." (PMID 26656588, 2015). "In a previous study, we have shown that although LYVE-1 expression on LVs located at the tumour periphery was strong, no or weak immunoreactivity was found in intratumoral LVs and that podoplanin is the best marker to visualise LVs in and around primary breast tumours." (PMID 17088912, 2006). "To further explore the potential role of these molecules in tumor lymphangiogenesis, we next quantitated LYVE-1, VEGF-C and VEGF-D transcripts in the same tumor series finding that, as expected, expression of these genes was higher in the more aggressive ER− breast tumors." (PMID 27806339, 2016).
myocardial infarction (6 papers, 2021 to 2024). Gross necrosis of the myocardium, as a result of interruption of the blood supply to the area, as in coronary thrombosis. "The outer membrane macrophages with high expression of lymphatic vessel endothelial hyaluronic acid receptor 1 (LYVE1) limit inadaptable cardiac remodeling after myocardial infarction." (PMID 38774746, 2024). "In the heart, Lyve1+ resident macrophages act in a cardioprotective manner during myocardial infarction and are immunoregulatory and promote engraftment of cardiac allografts." (PMID 38127424, 2023). "We next performed left anterior descending coronary artery (LAD) ligation operation to induce acute myocardial infarction in Lyve1-Cre-S1pr1flox/wt mice." (PMID 36003911, 2022). "To further investigate whether Lyve1-Cre-S1pr1flox/wt mice influenced cardiac resident macrophage after myocardial infarction, we performed co-immunostaining of CCR2 and F4/80 in post-MI hearts." (PMID 36003911, 2022). "Moreover, the importance of this LYVE-1 • HA axis for in vivo macrophage trafficking was recently demonstrated in a mouse model of myocardial infarction (MI), induced by ligation of the coronary artery." (PMID 34440831, 2021).
Cirrhosis (5 papers, 2019 to 2025). A chronic disorder of the liver in which liver tissue becomes scarred and is partially replaced by regenerative nodules and fibrotic tissue resulting in loss of liver function. "Gene expression of LV markers, PDPN (8-fold), and LYVE1 (3-fold) was enhanced in D2-biopsies of cirrhosis patients compared to control (p < 0.0001)." (PMID 37304826, 2023). "Recent studies have indicated that LYVE-1 expression is reduced in vivo in late-stage fibrosis and cirrhosis, a trend which we do broadly see in our data." (PMID 36345318, 2022). "Our study reports that patients with cirrhosis have a significantly increased number of lymphatic channels characterized by PDPN and VEGF-C immunostaining and PDPN and LYVE1 expression in the D2-biopsy lysates." (PMID 37304826, 2023). "LYVE1 (4-fold) and PDPN (9-fold) mRNA levels were elevated in patients with cirrhosis compared to controls (p < 0.0001)." (PMID 37304826, 2023). "LSECs of cirrhosis patients produce IVCol, fibronectin, and laminin, lose their characteristic fenestrations, and the expression levels of LSEC receptors LYVE-1, FcγRIIb and stabilin are decreased." (PMID 30695042, 2019). "Interestingly, liver inflammation and fibrosis further affect the LSEC molecular phenotype, leading to downregulation of LYVE-1 in liver cancer and cirrhosis, and of FcγRIIb in non-alcoholic steatohepatitis." (PMID 33246411, 2020).
liver disease (5 papers, 2013 to 2024). "Previously, increased intestinal expression of LYVE1 was reported in experimental models of portal hypertension." (PMID 35884808, 2022). "We observed herein that PCs can affect the lymphatic vasculature since the absence of this cell population was associated with reduced intestinal and mesenteric lymphatic vessels, determined by LYVE-1 immunostaining, in portal hypertensive mice." (PMID 35884808, 2022). "The European Association for the study of liver disease published recommendation in 2012 that “immunostaining for GPC3, HSP70, and glutamine synthetase and/or gene expression profiles (GPC3, LYVE1, and survivin) is recommended to differentiate high grade dysplastic nodules from early HCC." (PMID 24369506, 2013). "Capillarization of LSEC is commonly observed in liver disease and is well known to be accompanied by the downregulation of LSEC-characteristic transmembrane proteins such as CD32b and Lyve-1 and the upregulation of proteins characteristic of continuous EC such as Endomucin (Emcn)." (PMID 37446152, 2023).
liver fibrosis (5 papers, 2022 to 2025). "Immunohistochemical staining for LYVE1, a marker of LSECs, showed that LYVE1 expression was downregulated during liver fibrosis and was accompanied by disorganization of LSECs." (PMID 39194690, 2024). "The decreased expression of LYVE-1 is associated with the loss of LSEC fenestration in inflamed or fibrotic livers, which is observed to be negatively correlated with liver fibrosis." (PMID 37999580, 2023). "Arsenic-suppressed H3K18ac could trigger the dedifferentiation of LSECs via the inhibiting transcriptional activation of Fcgr2b and Lyve1, which are key genes responsible for maintaining the differentiation phenotype of LSECs, thereby promoting liver fibrosis." (PMID 37999580, 2023). "Immunostaining for Lyve1 (marker of differentiated LSECs) was reduced in Vcam1fl/fl mice and restored in Vcam1Δend mice in both NASH and liver fibrosis models." (PMID 36091042, 2022). "Taken together, these findings illustrate the complexities of LYVE-1 expression in different stages of fibrosis and suggest that directly associating the relative stage of liver fibrosis with a particular level of LYVE-1 expression may not always be appropriate." (PMID 36345318, 2022).
prostate carcinoma (5 papers, 2011 to 2021). A carcinoma that arises from epithelial cells of the prostate gland. "In prostate cancer, LYVE1 was found to be downregulated and associated with the relapse of localized prostate cancer." (PMID 31803141, 2019). "To further elucidate the role of PKCζ in lymphatic metastasis in prostate cancer, we performed immunohistochemistry (IHC) to investigate the lymphatic vessel marker LYVE-1 by staining the tissues dissected from mouse xenografts." (PMID 30705401, 2019). "Co-immunofluorescent staining for HAS2 and LYVE-1 showed that a portion of prostate cancer cells that localized in the lymphatic vessels expressed dramatically higher levels of HAS2, with significant differences in the level of HAS2 in prostate cancer cells outside or inside the lymphatic vessels." (PMID 30705401, 2019).
rheumatoid arthritis (5 papers, 2017 to 2025). A chronic, systemic autoimmune disorder characterized by inflammation in the synovial membranes and articular surfaces. "Yoo identified that exosomal serum amyloid A (SAA) and lymphatic endothelial hyaluronic acid receptor-1 (LYVE-1) were important in the rheumatoid arthritis (RA) pathogenic process and could serve as novel biomarkers of activity and remission." (PMID 40444241, 2025). "In clinically unremitting rheumatoid arthritis patients, serum LYVE1 levels were positively correlated with CRP." (PMID 38135837, 2024). "In fact, previous studies have reported the connection of serum soluble LYVE1 (sLYVE1) level with lymphoproliferative diseases such as cancer and rheumatoid arthritis." (PMID 38135837, 2024). "Along these lines, Lyve1-positive macrophages were proposed to exert pro-angiogenic functions and further seem to play an important role in inflammatory conditions like rheumatoid arthritis." (PMID 37998039, 2023).